ANKRD40 (ankyrin repeat domain 40)
Synonyms: MGC15396
Tractability: PROTAC: ubiquitination databases record sites on it.
Gene: Protein-coding gene on chromosome 17 (50,693,198 to 50,707,914, reverse strand). Ensembl gene ENSG00000154945.
Subcellular location (Human Protein Atlas): Golgi apparatus; Cytosol; Nucleoli fibrillar center
Gene Ontology:
Molecular function: protein binding
Genetic constraint (gnomAD): Loss-of-function variants: 24 observed, 36.06 expected, observed/expected ratio (o/e) 0.67, 90% interval 0.48 to 0.94. The upper end of that interval is the gene's LOEUF score, 0.94, which puts it in group 3 of 6, group 1 being the genes least tolerant of losing a copy. Missense variants: 361 observed, 447.86 expected, observed/expected ratio (o/e) 0.81, 90% interval 0.74 to 0.88. Synonymous variants: 147 observed, 180.41 expected, observed/expected ratio (o/e) 0.81, 90% interval 0.71 to 0.93.
Homologues: Orthologues: chimpanzee ANKRD40 (99% identical), macaque ANKRD40 (98% identical), rabbit ANKRD40 (96% identical), pig ANKRD40 (95% identical), dog ANKRD40 (93% identical), mouse Ankrd40 (92% identical), rat Ankrd40 (92% identical), guinea pig ANKRD40 (92% identical), rat Ankrd40 (80% identical), zebrafish ankrd40 (53% identical), tropical clawed frog ankrd40 (53% identical). Paralogues in human: ANKRD40CL (19% identical).
Diseases named in the same sentence as ANKRD40 in open-access papers:
ANKRD40 is named in the same sentence as 2 diseases in open-access papers, as found by Europe PMC text mining. Sharing a sentence is not in itself a finding about the gene and the disease. The quoted sentences say what the papers report.
breast carcinoma (1 paper, 2021). "The remaining four have all been studied for their effects in the development and maintenance of human breast cancers (TNP1, FST, ANKRD40, TRH)." (PMID 33957863, 2021).
tumor (1 paper, 2013). "ANKRD40, HNRNPF, IQGAP2, OTUD7B, and THAP5 mutations were detected in 1 tumor, each." (PMID 24223926, 2013).